SHBG (sex hormone binding globulin)
Diseases named in the same sentence as SHBG in open-access papers (continued):
Sharing a sentence is not in itself a finding about the gene and the disease.
breast cancer (continued). "IBIS-II was carried out on women who had other risk factors for breast cancer and it will be necessary to evaluate what approach is best for women without other known risk factors and how the E2/SHBG ratio can be integrated into the Tyrer-Cuzick model." (PMID 40973715, 2025). "Metabolic abnormalities and alterations in SHBG levels contribute to an imbalance in circulating sex hormone levels, thereby impacting the reproductive system and associated disorders such as polycystic ovary syndrome (PCOS), breast cancer, or infertility." (PMID 40427034, 2025). "We describe the relationship between plasma levels of oestradiol and its major protein binder, sex hormone binding globulin, on the development of oestrogen receptor positive breast cancer and how these impact on the preventive effect of the AI, anastrozole, in postmenopausal women." (PMID 40973715, 2025). "Integrating measurements of testosterone, SHBG, and CRP into diagnostic models could enhance breast cancer detection, particularly among individuals of normal weight." (PMID 39791640, 2024). "Similarly, SHBG protein has been shown to strongly impede MCF-7 breast cancer cell survival and proliferation by inhibiting the phosphorylation of Erk-1/-2." (PMID 38874666, 2024). "Finally, transcriptomics and proteomics data revealed that SHBG expression in breast tissue can effectively distinguish breast cancer from normal tissue." (PMID 38465341, 2024). "However, there is a paucity of research on the correlation between local SHBG expression and breast cancer." (PMID 38465341, 2024). "Insulin may directly impact breast cancer risk by mitogenic properties, increasing IGF-I secretion and decreasing IGF-I binding proteins, inhibiting sex hormone-binding protein (SHBG) synthesis, and raising bioavailable estrogen levels." (PMID 38999846, 2024). "In addition, by preventing estradiol from upregulating bcl-2, c-myc, and EGFR, SHBG is conducive to the recovery of the apoptosis mechanism of breast cancer cells." (PMID 38465341, 2024). "The mechanisms for the three cancers that this study supports are, for breast cancer, a decrease in sex-hormone-binding globulin and hormonal factors; for colorectal cancer, steroid hormones and chronic inflammation; and for renal cell carcinoma, an increased level of estrogen." (PMID 38794688, 2024). "Additionally, excess insulin inhibits hepatic sex hormone-binding globulin synthesis, resulting in elevated estrogen bioactivity and promoting breast cancer progression." (PMID 38279158, 2024). "Despite numerous studies on the impact of SHBG in plasma on breast cancer risk, there remains a lack of research into the effects of local SHBG expression within the breast." (PMID 38465341, 2024). "In fertile women, insulin and IGF-1 inhibit the hepatic synthesis of sex hormone-binding globulin (SHBG), increasing the bioavailability of estrogen, which may account for the increased risk of breast cancer." (PMID 37886939, 2023). "Otherwise, SHBG has been found to inhibit MCF-7 breast cancer cells growth via the direct blockade of ERK1/2 factors, while it has been demonstrated to stimulate the proliferation of the prostate cancer cell line, ALVA-41throught the increase in intracellular cAMP levels." (PMID 37402098, 2023). "It is well-established that low SHBG could lead to multiple unfavorable health outcomes, including a higher risk of PCOS, breast cancer incidence and mortality, type 2 diabetes (T2D), and several cardiovascular diseases." (PMID 35493382, 2022). "Previous studies revealed that a low serum SHBG concentration was positively correlated with a higher risk of polycystic ovary syndrome (PCOS) and PCOS-related metabolic disturbances, breast cancer incidence and mortality, type 2 diabetes (T2D), and cardiovascular disease risk." (PMID 35493382, 2022).
breast cancer (continued). "The effect of both testosterone and SHBG on ER-stratified breast cancer has been previously studied, in which both total (OR = 1.19, 95% CI:1.12, 1.26) and bioavailable testosterone (OR = 1.23, 95% CI:1.12, 1.34) were associated with increased risk of ER-positive breast cancers." (PMID 35061662, 2022). "The consortium reported significant associations of breast cancer risk with total testosterone, SHBG, IGF-1 and total and calculated free oestradiol in pre-menopausal women and with total testosterone, SHBG and IGF-1, as well as with total and calculated free oestradiol, in post-menopausal women." (PMID 33864017, 2021). "Meta-analyses suggest that high levels of SHBG are protective against breast cancer." (PMID 32847607, 2020). "The current data suggest that any influence of SHBG on the risk of breast cancer is likely independent of MD." (PMID 32847607, 2020). "Several mechanisms have been proposed to explain the potential protective effect of pregnancy on breast cancer, such as decreased levels of estrogen and progesterone, increased levels of sex hormone-binding globulin, and pregnancy-induced differentiation of breast tissue." (PMID 29338058, 2018). "We did not observe an association between SHBG and breast cancer risk in our study, which is also consistent with prior evidence." (PMID 23777922, 2013). "We did not observe an association between potential functional genetic polymorphisms in the estrogen pathway, SHBG rs6259, ESR1 rs2234693, CYP19 rs10046 and rs4775936, and UGT1A1 rs8175347, or the progesterone pathway, PGR rs1042838, with the risk of breast cancer." (PMID 23935996, 2013). "In addition, insulin and IGF1 inhibit the expression of sex-hormone binding globulin (SHBG), resulting in increase in estrogen bioavailability, a breast cancer risk factor in post-menopausal women." (PMID 23964270, 2013). "No variant associated with estradiol, testosterone, or SHBG at P<10–5 was associated with postmenopausal breast cancer risk among CGEMS participants." (PMID 22675492, 2012). "If SHBG gene expression is indeed modulated in prostate and breast cancer, this could alter their androgen and estrogen responsiveness." (PMID 19416531, 2009). "The possible biological mechanism is not clear, but in vitro studies also showed that lignan ENL in the presence of oestrogens suppressed the oestrogen-induced proliferation in MCF-7 breast cancer cell and stimulated the synthesis of sex hormone-binding globulin in liver cells." (PMID 18212757, 2008). "Although it is therefore possible that lignans increase SHBG levels, this effect did not translate into a reduction in risk of breast cancer in our study." (PMID 15226762, 2004). "The associations between serum concentrations of oestradiol, progesterone, testosterone and sex hormone-binding globulin (SHBG) and risk of breast cancer in premenopausal women were investigated in a prospective study of breast cancer on the island of Guernsey." (PMID 9083346, 1997). "In addition oestradiol levels were measured in relation to sex hormone binding globulin (SHBG), albumin levels, oestrogen receptor status and family history of breast cancer." (PMID 2393409, 1990). "In line with emerging literature, our data support the role of SHBG as both a proxy marker of insulin sensitivity and exposure, hepatic function, as well as a potential diagnostic biomarker and therapeutic target in the management of PCOS, MASLD, and breast cancer." (PMID 41586225, 2025). "Therefore, testing for SHBG concentration in patients with breast cancer may be justified, as is potential testing for alterations in the SHBG gene." (PMID 40427034, 2025). "Besides, recent studies reported on the hormone-like effects of SHBG on proximal tubule epithelial cells, breast cancer, and our earlier studies demonstrated that SHBG modulates hepatocytes viability and lipolytic genes expression, and finally protects against ER stress." (PMID 37402098, 2023).
breast cancer (continued). "In addition, the incubation of cells with SHBG resulted in the accumulation of cyclic adenosine monophosphate (cAMP) as detected in cytotrophoblasts or in MCF-7 breast cancer cells, which could be further increased by the addition of steroid ligands." (PMID 30626909, 2019). "Several studies have also shown an increase in breast cancer risk among women who have increased testosterone levels, reduced levels of sex hormone-binding globulin (SHBG), and hence elevated levels of bioavailable androgens and estrogens not bound to SHBG." (PMID 24911052, 2014). "The roles of sex hormones such as estradiol, testosterone, and sex hormone-binding globulin (SHBG) in the etiology of lung and colorectal cancers in women, among the most common cancers after breast cancer, are unclear." (PMID 38659935, 2024). "In premenopausal women with breast cancer, a significant decrease in estradiol, progesterone, testosterone, DHEAS, and SHBG (all P < 0.001) levels was found." (PMID 36117838, 2022). "SHBG, for example, inhibits estrogen’s anti-apoptotic effects in MCF-7 cells, a breast cancer cell line." (PMID 36266625, 2022). "Amongst females, an increased risk of breast cancer was observed with increasing total (OR = 1.15, 95% CI: 1.07, 1.23 per SD) and bioavailable (OR = 1.10, 95% CI: 1.01, 1.19 per SD) testosterone, but not in relation to SHBG (OR = 0.99, 95% CI: 0.89, 1.11 per SD)." (PMID 35061662, 2022). "Observational studies and RCTs of women at risk of breast cancer have determined that higher levels of physical activity result in statistically significant reductions in estradiol, free estradiol, and estrone, while increasing levels of SHBG, regardless of menopausal status." (PMID 32741068, 2021). "We aim at investigating the impact of BMI on the hormonal state of breast cancer (BC) patients receiving anastrozole indicated by LH, FSH and SHBG as well as estradiol." (PMID 28351392, 2017). "It binds with high affinity to a specific membrane receptor (RSHBG), forming the SHBG-RSHBG complex, and an appropriate steroid binds to this complex and increases intracellular cAMP in prostate and breast cancers." (PMID 24386165, 2013). "Therefore, SHBG disrupts the loop connecting the two pathways by inhibiting estradiol-induced EGFR expression, thereby reducing the growth of breast cancer cells." (PMID 38465341, 2024). "Although elevated levels of SHBG can serve as early detection markers for gastric cancer, however, this is not the case for breast cancer." (PMID 39075362, 2024). "In obese postmenopausal women, resveratrol significantly increases sex hormone-binding globulin (SHBG) levels, which are negatively associated with breast cancer risk, without markedly affecting serum estrogen and testosterone concentrations." (PMID 39872049, 2024). "In agreement with the largest meta-analyses of epidemiological studies to date, we did not observe an association for SHBG rs6259, PGR rs1042838, ESR1 rs2234693, CYP19 rs10046 and rs4775936, and UGT1A1 rs8175347 and breast cancer risk." (PMID 23935996, 2013). "In tissue samples from breast cancer patients, the proliferation rate of samples with a steroid-binding protein receptor bound with SHBG was reduced significantly compared to samples that could not bind with SHBG." (PMID 38465341, 2024). "However, this review did not uncover evidence that concentrations of either SHBG or estradiol were related to breast cancer recurrence." (PMID 36401194, 2022). "The LNCaP (prostate cancer) and MCF-7 (breast cancer) cell lines express SHBG at the mRNA and protein levels and possess RSHBG activity, making them attractive in vitro models for studying the effects of local SHBG expression on steroid signaling and RSHBG regulation." (PMID 19416531, 2009).
breast cancer (continued). "While reduced SHBG increases the fraction of bioavailable estradiol and testosterone, increasing risk for hormone-responsive tumors; elevated IGF-1 could stimulate the growth of breast cancer cells in absence of ER or PR activation." (PMID 26352264, 2015). "Although women with breast cancer tend to have a greater proportion of their circulating oestradiol non-protein bound and albumin bound, and less SHBG-bound, than controls, it remains uncertain whether this has an aetiological role or is an effect of the tumour." (PMID 2310682, 1990). "Interestingly, although they were not identified as clinically significant in breast cancer, cBioPortal analyses revealed significantly decreased levels of IGF1 mRNA and elevated levels of SHBG mRNA in Black samples in both BRCA-P and BRCA-C studies." (PMID 37345032, 2023).
type 2 diabetes (150 papers, 2007 to 2026). "The same study reported that the risk of type 2 diabetes increased as the concentration of serum SHBG decreased to <40 in men and <50 nmol/L in women." (PMID 40892850, 2025). "This is in accordance with several previous studies, where the relationship between low serum SHBG and increased risk of lipid metabolic disease and type 2 diabetes were more pronounced in women compared to men." (PMID 40532849, 2025). "Several studies have identified PNPLA3 as being associated with testosterone and SHBG levels, and it has also been linked to type 2 diabetes." (PMID 40892850, 2025). "In relation to this, several studies have shown that low serum SHBG in overweight individuals is associated with an increased risk of metabolic syndrome, type 2 diabetes, and cardiovascular disease." (PMID 40532849, 2025). "There is credible evidence that low levels of SHBG are also a key risk factor to the development of type 2 diabetes, with a 2015 meta-analysis indicating the connection between SHBG and the adverse influence of excess testosterone on glucose metabolism." (PMID 39458485, 2024). "The metabolic role of SHBG has also been described by several observational studies which showed an association between impaired SHBG concentrations with an increased incidence of type 2 diabetes." (PMID 39590862, 2024). "Previous MR studies have suggested the protective role of SHBG against the development of metabolic disorders, such as type 2 diabetes and hypertension, both risk factors for fatty liver." (PMID 37900132, 2023). "Overall, type 2 diabetes was associated with decreased total testosterone (β: -0.021,95%CI: -0.032, -0.010, p<0.001) and sex hormone binding globulin (β: -0.048, 95%CI: -0.065, -0.031, p<0.001)." (PMID 37900148, 2023). "We found that the association between IHL content and type 2 diabetes was statistically significantly mediated by serum SHBG in men (OR 1.02 [95% CI 1.01, 1.03]) and women (OR 1.04 [95% CI 1.02, 1.07])." (PMID 36114428, 2023). "During a 5 years follow-up, men with the lowest SHBG levels had a four-fold higher risk of type 2 diabetes." (PMID 36968815, 2023). "Lastly, there was a statistically significant inverse association between serum SHBG and type 2 diabetes status in men and women (OR 0.96 [95% CI 0.95, 0.98] and OR 0.98 [95% CI 0.97, 0.99], respectively)." (PMID 36114428, 2023). "Of interest, Mendelian randomisation studies have shown that genetically predicted low serum SHBG levels are associated with a higher risk of type 2 diabetes." (PMID 36114428, 2023). "It is likely that there are several pathways that mediate the association between IHL content and type 2 diabetes, of which serum SHBG is merely one." (PMID 36114428, 2023). "In a large cohort study including 42,034 women, a higher risk of type 2 diabetes was associated with SHBG levels < 50 nmol/L." (PMID 36968815, 2023). "Currently, SHBG has been identified as a disease risk biomarker; its level is inversely associated with metabolic syndrome and type 2 diabetes, whereas it is positively associated with HDL-cholesterol concentration." (PMID 36550468, 2022). "Prior studies indicated that higher levels of testosterone and sex hormone-binding globulin (SHBG) in middle-aged males are associated with a reduced risk of metabolic syndrome and women with type 2 diabetes (T2D) had lower SHBG levels." (PMID 35741728, 2022). "The association between low SHBG levels and increased risk of development of type 2 diabetes was supported by the Rotterdam study including 3,177 postmenopausal women, with a median observation of 11.1 years." (PMID 35140785, 2022). "Higher genetically predicted SHBG levels were associated with a reduced risk of hypertension, type 2 diabetes, diabetic complications, coronary atherosclerotic outcomes, gout and neoplasm of uterus, and an increased risk of varicose veins and fracture." (PMID 35218343, 2022).